MC4R (melanocortin 4 receptor)
Diseases named in the same sentence as MC4R in open-access papers (continued):
Sharing a sentence is not in itself a finding about the gene and the disease.
Obesity (continued). "These justify the interaction observed between MC4R rs17782313 variants and dietary carbohydrate intake on indices of obesity." (PMID 35538513, 2022). "Our study revealed that the relation of carbohydrate intake to BMR and measures of obesity depends on MC4R polymorphism." (PMID 35538513, 2022). "MC4R mutations are associated with early-onset severe obesity, and the identification of potential pathological variants is crucial for the clinical management of patients with obesity." (PMID 35807283, 2022). "In humans, the most common forms of monogenic obesity are associated with mutations that disrupt the melanocortin-4 receptor (MC4R) signaling in the hypothalamus." (PMID 34943946, 2021). "A mediation analysis confirmed that the association between the MC4R p.Ile269Asn mutation and T2D was not only explained by its obesity-predisposing effect." (PMID 33542413, 2021). "It has previously been demonstrated that the MC4R-rs17782313 polymorphism is strongly related to obesity in adults and children of European descent." (PMID 34696776, 2021). "R165W is a mutation reported in several obese patient cohorts and is representative of a large number of obesity-causing MC4R mutations resulting from misfolding and intracellular retention of the receptor." (PMID 33434184, 2021). "Loss of function of MC4R in the hypothalamus results in obesity, hyperphagia, reduction of sympathetic nerve activity (SNA) tone, and decrease in energy expenditure, hyperinsulinemia, and increased triglycerides accumulation in the liver." (PMID 34943946, 2021). "The onset of hyperglycemia in adult Mc4r deficient mice is mainly explained by obesity-induced insulin resistance." (PMID 33542413, 2021). "MC4R deficiency is the commonest known monogenic obesity disorder resulting in increased lean body mass, bone mineral density, and linear growth as well as hyperphagia and severe hyperinsulinemia." (PMID 34451881, 2021). "These genes were strongly connected, and FTO and MC4R acted as hub genes that affect the risk of obesity." (PMID 34836030, 2021). "Ataluren was not either effective in reading-through premature stop codons in an obesity-associated gene encoding melanin 4 receptor (MC4R) in the hypothalamus." (PMID 34451881, 2021). "With respect to genetic association of the four selected gene polymorphisms, FTO rs9939609 and MC4R rs17782313 were found to be associated with obesity." (PMID 34414818, 2021). "Mutations in Mc4r are the most common monogenic cause of severe obesity in humans, as well as in rodents." (PMID 34211092, 2021). "The melanocortin-4 receptor (MC4R) gene harbours one of the strongest susceptibility loci for obesity and obesity-related metabolic consequences." (PMID 34769477, 2021). "To explore the potential of a PC therapeutic approach in the context of MC4R deficiency in humans, we generated knockin (KI) mouse lines expressing the WT or an obesity-causing mutant form of the hMC4R in the receptor’s mouse locus." (PMID 33434184, 2021). "Mutations in the melanocortin 4 receptor gene (MC4R) are associated with obesity but little is known about the prevalence and impact of such mutations throughout human growth and development." (PMID 34045736, 2021). "To date, liraglutide treatment was effective on obesity in 7 subjects with Prader Willy Syndrome and 14 with melanocortin-4 receptor mutations." (PMID 34239499, 2021). "Considering the close connection between metabolic gene polymorphisms and obesity, the possibility that these targets (e.g., MC4R, FTO, PPARγ) in obese patients are more directly related to severe COVID-19 than BMI cannot be excluded." (PMID 34373739, 2021). "As the most common monogenic cause of obesity, deficient MC4R and the central melanocortin pathway together regulate energy intake, expenditure, and homeostasis." (PMID 34373739, 2021). "For instance, MC4R knockdown mice were severely obese and the loss of one MC4R allele resulted in an intermediate obesity phenotype." (PMID 34696776, 2021).
Obesity (continued). "Both models are MC4R dependent and recapitulate many of the characteristics of human obesity resulting from deficiencies in the melanocortin system, such as increased food intake, weight gain, hyperglycemia, and increased linear growth." (PMID 33434184, 2021). "In the mouse, targeted deletion of Mc4r causes weight gain, early onset obesity and increased linear growth." (PMID 33937937, 2021). "MC4R mutations represent the largest monogenic cause of obesity, resulting mainly from receptor misfolding and intracellular retention by the cellular quality control system." (PMID 33434184, 2021). "Melanocortin-4 receptor (MC4R) mutations are the most common of the rare monogenic forms of obesity." (PMID 35095762, 2021). "The MC4R rs17782313 variant was associated with the obesity-related proteins ghrelin and visfatin in the Arabic population." (PMID 34205732, 2021). "While obesity is commonly associated with sympathetic overactivity and elevated blood pressure (BP), severely obese MC4R knockout mice exhibit normal to reduced sympathetic nerve activity (SNA) when compared to their lean wild-type littermates." (PMID 34262481, 2021). "The biological mechanism underlying the association between MC4R and obesity, has been widely studied." (PMID 33804309, 2021). "Further, after controlling for the interaction effect, only MC4R rs17782313 was seen to confer risk for obesity in terms of high WHtR among Liangmai whereas FTO rs9939609 was seen to pose significantly reduced risk for WHtR." (PMID 34414818, 2021). "Based on structural mapping of obesity-associated mutants, we predicted that human MC4R can form homodimers; this assertion was validated in cells using two independent experimental approaches." (PMID 33761344, 2021). "Within the hypothalamus, the dorsomedial hypothalamus (DMH) was also shown to be involved in the increase in BP caused by higher leptin levels in diet-induced obesity, possibly via MC4R." (PMID 34512392, 2021). "Common polymorphic variants near the MC4R gene, which encodes the hypothalamic melanocortin 4 receptor, are widely recognized genetic risk factors linked with early-onset severe obesity." (PMID 34445769, 2021). "This variant as well as its proxy markers (e.g., rs17782313) near the MC4R gene have been associated with obesity in previous publications." (PMID 32952152, 2021). "The prevalence of MC4R mutations in obese people varies substantially in frequency (1%–6% of the obese patients) depending on the ethnic origin, the severity of obesity, and the age of obesity onset of the population considered." (PMID 33434184, 2021). "Loss of MC4R function is accompanied by hyperphagia, development of obesity and insulin resistance, cardiovascular abnormalities, and fatty liver in mice and humans." (PMID 34943946, 2021). "The high-throughput assay to quantitatively measure ligand-activated MC4R-induced [Ca2+]iin vitro has potential to advance development of therapeutic drugs and understanding about MC4R signalling associated with human obesity." (PMID 33739935, 2021). "For example, single-nucleotide polymorphisms (SNPs) in the FTO gene are associated with higher risk of obesity and type 2 diabetes, while SNPs in the MC4R gene are associated with increased fat mass and obesity risk." (PMID 33588846, 2021). "Evidence for the causative gene MC4R was selected a priori as a candidate gene based on its known function in body weight and obesity in other species." (PMID 34461824, 2021). "To address the therapeutic value of PCs in vivo to treat MC4R-linked obesity, we generated humanized MC4R knockin mouse lines expressing either the WT or an obesity-causing mutant form of the human MC4R (hMC4R) in the receptor’s mouse locus." (PMID 33434184, 2021).
Obesity (continued). "The present study showed the participants with high PRS of appetite-related genes, mainly MC4R pathway-related genes, including SEC16B_ rs543874, BDNF_ rs6265 DNAJC27_ rs713586, MC4R_rs17782313, GIPR_ rs1444988703, increased the obesity risk by 1.6-fold." (PMID 34836030, 2021). "This study provides compelling evidence that the MC4R p.Ile269Asn mutation confers high-risk for T2D via obesity-dependent and independent mechanisms in the Mexican population." (PMID 33542413, 2021). "Common variants in MC4R have been associated with a moderately increased risk of obesity, already in the early genome-wide association studies (GWAS) on body mass index (BMI)." (PMID 33804309, 2021). "Recently, a large-scale GWA study on individuals from the UK Biobank showed that variants around MC4R protect against obesity in humans." (PMID 34411094, 2021). "Those individuals with severe obesity developed before two years old should consult obesity medicine specialists and consider to be involved in screening for MC4R Deficiency, leptin deficiency, and POMC deficiency." (PMID 34552557, 2021). "The majority of the studies reported significant increased association with obesity and MC4R rs17782313; however, discrepancies were observed, especially among the East Asian and Africans." (PMID 34414818, 2021). "Knockout mice for POMC or MC4R are hyperphagic and obese and, in humans, mutations in the POMC and MC4R genes produce severe obesity." (PMID 34068091, 2021). "The number of identified MC4R mutations exceeds 369, and MC4R deleterious mutations are responsible for an autosomal co-dominant form of monogenic obesity." (PMID 32921795, 2021). "In conclusion, we demonstrate that the MC4R p.Ile269Asn mutation confers high risk for T2D via obesity-dependent and independent effects in the Mexican population." (PMID 33542413, 2021). "Around 6% of children with severe early-onset (age < 10 years) obesity have a pathogenic mutation in MC4R." (PMID 33804309, 2021). "For instance, some obesity-causing mutations in melanocortin receptor 4 (MC4R) act by preventing its ciliary targeting, thereby perturbing adenylyl cyclase 3 (AC3)-dependent cAMP signaling in hypothalamic cilia." (PMID 33372037, 2021). "The penetrance estimation for BMI and obesity from this collection will assist variant reclassification for MC4R and improve clinical decision making in the context of personalized medicine." (PMID 32952152, 2021). "In conclusion, a PRS model using SEC16B_rs543874, DNAJC27_rs713586, BDNF_rs6265, MC4R_ rs6567160, and GIPR_rs1444988703 had gene−gene interactions which elevated the obesity risk." (PMID 34836030, 2021). "Targeted deletion of MC4R gene is associated with early-onset severe obesity, hyperphagia, and hyperinsulinemia." (PMID 33716796, 2021). "The third strongest signal was observed closest to the MC4R gene (index SNP rs663129, Pmeta = 3.10 × 10− 18), which is involved in the leptin signaling pathway and its disruption is a causal factor of obesity." (PMID 33910581, 2021). "This robust, reproducible, high-throughput assay that quantitatively measures MC4R-induced mobilisation of [Ca2+]iin vitro has potential to advance the development of therapeutic drugs and understanding of MC4R signalling associated with human obesity." (PMID 33739935, 2021). "Melanocortin 4 receptor (MC4R) deficiency is the commonest monogenic form of obesity, and results in severe obesity." (PMID 33806715, 2021). "While MC4R partial and complete deficiency results in hyperphagia and oligogenic/monogenic obesity in mice and humans, there is limited evidence in the literature linking MC4R to T2D9,14." (PMID 33542413, 2021). "In our cohort of children and adolescents with overweight or obesity, we identified 30 carriers of damaging or unresolved MC4R mutations (2.5%)." (PMID 32921795, 2021). "MC4R-associated obesity is the most common monogenic form of obesity with a reported prevalence of up to 6%." (PMID 32952152, 2021).
Obesity (continued). "To test the therapeutic PC potential, we engineered humanized MC4R (hMC4R) mouse models expressing either the WT human MC4R or a prevalent obesity-causing mutant (R165W)." (PMID 33434184, 2021). "According to GWAS, melanocortin 4 receptor (MC4R) gene was reported to the second strongest gene in the causes of obesity next to FTO gene." (PMID 34414818, 2021). "In conclusion, we created 2 new obesity models, a hypomorphic highlighting species differences and an amorphic providing a preclinical model to test the therapeutic potential of PCs to treat MC4R-linked obesity." (PMID 33434184, 2021). "The single nucleotide polymorphism (SNP) rs17782313 near the MC4R gene has been linked to obesity, and a previous study using magnetoencephalography has shown that carriers of the mutant allele have decreased cerebrocortical response to insulin." (PMID 33806715, 2021). "Rare mutations in the MC4R gene have consistently been associated with monogenic obesity; however, most cases of obesity and T2DM result from polygenic and multifactorial interactions, including MC4R gene SNPs." (PMID 34769477, 2021). "Together, these results demonstrate that recruitment of β-arrestin-2 to MC4R is a key mechanism that governs its internalization and signaling, and one which can be impacted by human obesity-associated and obesity-protecting mutations." (PMID 33761344, 2021). "The role of mutations in MC4R in human monogenic obesity was described in the late 1990s and has also been described to affect variation in fatness, growth, and feed intake in different pig breeds." (PMID 34551713, 2021). "Generally, the combined effect of FTO rs9939609 and MC4R rs17782313 was significantly associated with obesity in various populations." (PMID 34414818, 2021). "We demonstrate that the MC4R p.Ile269Asn mutation predisposes to T2D via obesity-dependent and independent effects in the Mexican population." (PMID 33542413, 2021). "Among Danish children and adolescents with overweight or obesity entering a tertiary lifestyle intervention, 2.5% carried damaging or unresolved MC4R mutations." (PMID 32921795, 2021). "More recently, it was shown that rare to ultra-rare nonsynonymous variants in MC4R (allele frequency 0.0001–2%) are, next to obesity, also associated with type 2 diabetes and coronary artery disease." (PMID 33804309, 2021). "MC4R mutations represent the most prevalent form of monogenic obesity and both animal models and human patients carrying loss-of-function MC4R mutations exhibit early-onset obesity caused by hyperphagia and reduced energy expenditure." (PMID 34262481, 2021). "A much more common genetic variant rs17782313 (C/T polymorphism) near the MC4R gene has also been associated with obesity, and insulin resistance." (PMID 33806715, 2021). "Rare genetic mutations leading to melanocortin 4 receptor (MC4R) deficiency are an important monogenetic cause of obesity." (PMID 33804309, 2021). "The melanocortin 4 receptor gene, MC4R, is a key component of the melanocortin system, and its mutation is the most common monogenic cause of severe obesity." (PMID 34389046, 2021). "The researchers imply that the mutations near the MC4R gene region significantly increased the risk of obesity, diabetes mellitus, and psoriatic arthritis in the presented study group, although large-scale prospective studies are required." (PMID 34445769, 2021). "Structural mapping reveals ligand-accessible sites by which MC4R couples to effectors and residues involved in the homodimerization of MC4R, which is disrupted by multiple obesity-associated mutations." (PMID 33761344, 2021). "Subsequent studies found that mutations in MC4R and common genetic variation near MC4R lead to a dominant form of obesity and insulin resistance." (PMID 33807040, 2021). "We used human MC4R mutations associated with an increased or decreased risk of obesity to dissect mechanisms that regulate MC4R function." (PMID 33761344, 2021).
Obesity (continued). "A systematic review in 2021 synthesized outcomes of BS among patients with monogenic forms of obesity and found that weight loss results were inconsistent for patients with MC4R-d." (PMID 35095762, 2021). "A mutation in the melanocortin 4 receptor gene (MC4 R) is the most common gene defect, which is associated with a severe, early form of obesity in children." (PMID 34959873, 2021). "Currently, two gene variants, i.e., of MC4R, already known as the most common cause of monogenic obesity, and FTO-associated gene, have been identified, with small but replicable effects on body weight." (PMID 33261141, 2020). "Deletion of MC4R in mice causes hyperphagia and obesity, and MC4R gene mutation is also associated with severe early-onset obesity in human study." (PMID 33372630, 2020). "Several studies have reported the association of MC4R variants with obesity in various ethnic groups." (PMID 32733386, 2020). "The rare coding mutations in the MC4R gene have been found to be the main cause of human monogenic obesity, suggesting that the MC4R gene represents a compelling biological candidate." (PMID 32899047, 2020). "This research sought to test the MC4R rs17782313, rs476828 and rs12970134 SNPs, their haplotypes and gene-environment interactions on the risk of obesity in the Maonan ethnic group, an isolated minority in China." (PMID 32770936, 2020). "Here, we studied a cohort of European ancestry individuals with severe childhood-onset obesity (SCOOP) in whom known causes of monogenic obesity, such as congenital leptin deficiency and MC4R mutations, had been excluded (STAR Methods)." (PMID 32492392, 2020). "Upon closer observation of the relationship between the MC4R SNPs and their haplotypes and the risk of obesity, we noted that the rs17782313C-rs476828C-rs12970134A haplotype increased the risk of obesity." (PMID 32770936, 2020). "For example, obesity risk alleles in MC4R were shown to be associated with an increased caloric intake and a higher percentage of calories from fat; SH2B1 obesity risk alleles were linked to increased fat intake." (PMID 32228543, 2020). "The present study showed a modest increase in BMI in individuals with carrier genotypes of the rs17782313 variant near MC4R, although the allele-based association tests showed a significant risk for obesity, with an odds ratio of 1.5." (PMID 32733386, 2020). "Here, we first assess the impact of pathogenic MC4R mutations, previously implicated in severe and early onset obesity, in the UK Biobank, a large-scale population-based cohort of approximately 500,000 individuals living in the United Kingdom." (PMID 32692746, 2020). "MC4R-deficient mice are characterized by early onset of obesity associated with hyperphagia, hyperinsulinemia and hyperglycemia under a regular chow diet." (PMID 33374435, 2020). "Our findings show that large-scale population data are needed to more accurately assess the impact of MC4R mutations on extreme early onset obesity." (PMID 32692746, 2020). "MC4R rs2229616 C>T is a missense variant Val103Ile located in the coding region of chromosome 18 that provides vital protection against severe obesity." (PMID 31947684, 2020). "One of the strongest genes increasing susceptibility to obesity is the melanocortin-4 receptor (MC4R)." (PMID 32758123, 2020). "An MC4R deficiency results in obesity and many features of the metabolic syndrome, including insulin resistance, hyperinsulinemia, and increased visceral adiposity." (PMID 33817246, 2020). "MC4R has often been used as a target for obesity treatment because variants that result in decreased MC4R activity are associated with obesity." (PMID 32733386, 2020).